RNU6-763P (RNA, U6 small nuclear 763, pseudogene)
Gene: Small nuclear RNA gene on chromosome 2 (175,022,214 to 175,022,319, forward strand). Ensembl gene ENSG00000212167.
Homologues: Orthologues: chimpanzee U6 (99% identical), macaque U6 (93% identical), mouse Gm25875 (68% identical), rat LOC120093914 (62% identical). Paralogues in human: RNU6-41P (82% identical), RNU6-44P (82% identical), RNU6-968P (82% identical), RNU6-1083P (81% identical), RNU6-188P (81% identical), RNU6-20P (81% identical), RNU6-589P (81% identical), RNU6-842P (81% identical), RNU6-869P (81% identical), RNU6-1013P (80% identical), RNU6-1145P (80% identical), RNU6-12P (80% identical), and 1287 more.